ESR1 (estrogen receptor 1)
Diseases named in the same sentence as ESR1 in open-access papers (continued):
Sharing a sentence is not in itself a finding about the gene and the disease.
tumor (continued). "As expected, these results are concordant with the fact that immune response is triggered in ER-negative tumours, i.e. ESR1-low tumours." (PMID 33599248, 2021). "With the success in establishing estrogen-stimulated (SC31) and estrogen-suppressed (GS3) patient-derived xenograft (PDX) models, single-cell RNA sequencing analysis was performed to determine the impact of estrogen on ESR1+ and ESR1– tumor cells." (PMID 34944995, 2021). "ESR1 was identified as the real hub gene related to the recurrence of iCCA that plays a critical tumor suppressor role in iCCA progression." (PMID 33865377, 2021). "Taken together, the expression of ESR1 and PGR was significantly associated with pan-cancer tumor stage." (PMID 34322374, 2021). "ESR1 has been identified as a tumor suppressor protein whose expression inversely correlates with tumor size and disease stage, based on genome-wide expression and microRNA analyses." (PMID 34881186, 2021). "Tumours with an elevated expression of markers associated with luminal differentiation (KRT20, ERBB2, ESR1) were associated with a higher chance of pCR (55% vs. 15.8%, p = 0.009)." (PMID 34073233, 2021). "In particular, we discuss the impact of genetic alterations, chromatin modifications, and enhanced expression of other luminal transcription regulators on ESR1 expression in tumor cells." (PMID 34831189, 2021). "ESR1 (estrogen receptor alpha 1) has been recognized as a tumor-suppressor gene and an estrogen receptor gene." (PMID 34778269, 2021). "ESR1 has been recognized as a tumor suppressor gene, with promoter hypermethylation being predictive of tumor progression." (PMID 34881186, 2021). "We observed low ESR1 expression levels from eight datasets in four tumor types, consistent with ESR1 expression level in TCGA tumors." (PMID 32536040, 2020). "LMO1, RP11-834C11.12, MAN1A2P1, HTRA3 and ESR1 were the top five differentially hypermethylated genes in primary tumours compared to NAT." (PMID 32971738, 2020). "A novel SERD, known as AZD9496, showed anti-tumour activity of AZD9496 in the ESR1 Y537S mutant in in vitro models, with greater potency than fulvestrant." (PMID 32932819, 2020). "On the contrary, the mRNA level of ESR1 was much higher in residual tumor after NAC (GSE21997: p = 0.0166; GSE32646: p < 0.0001; GSE25055: p < 0.0001)." (PMID 33292226, 2020). "In vivo xenograft model revealed that ESR1-mutant tumours progressed faster to alpelisib plus oestrogen deprivation than parental tumours." (PMID 32641355, 2020). "The significant different DNA methylation between tumor and healthy tissues was shown in 10 tumor types for ESR1 and eight tumor types for ESR2." (PMID 32536040, 2020). "Evaluating the same 47 gene sets at the time of surgery compared to pre-treatment by GSEA, reductions in proliferation, ERBB2 signaling, and ESR1 signaling were observed, consistent with lower tumor content." (PMID 33203854, 2020). "High expression of ESR1 was ascertained in tumor tissues compared with normal tissues in BRCA, while other tumors showed low expression, including BLCA, COAD, CESC, CHOL, KICH, LIHC, PCPG, and READ." (PMID 32536040, 2020). "Analysis of the relative mRNA expression of estrogen receptor (ESR) 1 in isolated splenic NK cells of the short-term experiment showed a significantly decreased expression in control diet-fed animals receiving tumor cell injection compared to NaCl-injection." (PMID 33244094, 2020). "The silence of ESR1 significantly increased the size of tumor in HCC tissues, implying that ESR1 is a tumor suppressor in human HCC." (PMID 32308626, 2020). "We next further performed the cox regression analysis of ESR1/2 mRNA expression, DNA methylation and ERs protein expression levels in each tumor type." (PMID 32536040, 2020).
tumor (continued). "DNA methylation patterns in CGIs of ESR1, encoding for ERα, and BRCA1, an important tumor suppressor gene, have recently been examined, reporting changes in DNA methylation of these genes in malignant canine tumors." (PMID 32051475, 2020). "CYP19A1 mRNA expression was positively correlated with tumor size (r = 0.49; P < .05), whereas expression of ESR1 (ERα) mRNA was negatively associated with this variable (r = –0.54; P = .0296)." (PMID 31853538, 2020). "BasalIMG and LumAIMG tumor distributions are separated based on Mann-Whitney U test with p = 1.02 × 10−25 in ESR1 and p = 3.40 × 10−29 in PGR." (PMID 31992350, 2020). "This is supported by our reanalysis of RNA-seq from PCa tumours in which ESR1 was expressed in most samples." (PMID 32132580, 2020). "HNF1A, ESR1, and FLT4 were mutated significantly more frequently in tumor tissue samples obtained from patients with stage III BC, while SYNE1, PER1, and LRP1B were mutated significantly more frequently in stage IV BC." (PMID 32731384, 2020). "In July 2014, the primary tumor was biopsied and the first plasma sample was taken, showing no pathogenic or likely pathogenic variants in the PIK3CA or ESR1 gene." (PMID 31254045, 2020). "The number of ERs significantly correlated genes varies considerably in different tumor types (from 0 to 3679 for ESR1 and from 0 to 3667 for ESR2)." (PMID 32536040, 2020). "ESR1 mutant-driven estrogen-independent tumor growth was also validated in both ER+ cell xenografts and patient-derived xenograft (PDX) models." (PMID 31106278, 2019). "Functional analysis confirmed that 39 genes were associated with the processes of tumour formation and cancer progression of which two (PGR and ESR1) were common to four cancers of women." (PMID 31879572, 2019). "For example, tumours 250 and 337 are classified as MA by gene expression but luminal by IHC; they express AR well but they also express ESR1 at a level almost exactly at the cut-off separating luminal from MA tumours." (PMID 30899086, 2019). "While the ESR1 SNP rs3020410 (CC vs CA vs AA) was correlated with both estrogen receptor status (P = 0.012) and tumor size (P = 0.032)." (PMID 31888550, 2019). "As a candidate tumor suppressor gene, decreased ESR1 expression was significantly correlated to high liver damage score, pathological invasion, and tumor size." (PMID 31851620, 2019). "In ESR1 wild-type AI-resistant tumours ERG expression remained suppressed and was uncoupled from the recovery seen in proliferation." (PMID 30563991, 2019). "ESR1 increases cellular proliferation in tumor cell lines, such as lung, prostate and breast cancer cells." (PMID 31159758, 2019). "Despite such in-depth studies of transcriptional and growth-promoting properties endowed by ESR1 LBD point mutations, the role of such mutations in driving cell invasion and tumor metastasis is underexplored." (PMID 31106278, 2019). "After treatment, the tumor from one patient in the FEC/TE group became ESR1 positive, whereas in the FEC/TE + I2 group, 90% of the tumors (10 samples) were ESR1 positive." (PMID 31319484, 2019). "Another study using a patient-derived xenograft (PDX) model harboring an ESR1 amplification derived from a patient with endocrine-refractory disease demonstrated that tumor growth was suppressed with estradiol treatment." (PMID 31106278, 2019). "Further, next-generation sequencing (NGS) analysis was performed, and results revealed two tumour-related gene mutations (deletion of PMS2 and variation of ESR1 [L536P])." (PMID 31391089, 2019). "In separate multivariable models controlling for age, tumor size, and tumor grade, ESR1 by RT-PCR, PGR by RT‐PCR, and ER gene-group score were significant predictors of clinical response." (PMID 30242578, 2019). "Used as monotherapy or in combination with a hybrid SERM/SERD, bazedoxifene, palbociclib suppressed tumor growth of a WHIM20 PDX tumor harboring an ESR1-Y537S mutant." (PMID 31106278, 2019).
tumor (continued). "Microarray analysis of E2-stimulated tumours identified Greb1 as a highly upregulated gene, and we therefore investigated its role in ESR1-mediated tumour growth." (PMID 29973689, 2018). "In a multivariate logistic regression analysis, ESR1, PGR, and tumor mutation burden all were identified as independent factors predicting T cell infiltration." (PMID 30400835, 2018). "Treatment with aromatase inhibitors, a class of drugs that suppress the synthesis of estrogen, can drive the evolution of mutations in the estrogen receptor gene ESR1, leading to tumor resistance against hormone therapies." (PMID 30083595, 2018). "Gene expression analysis of the tumours showed that ESR1 likely mediates this effect, as Esr1 was highly expressed in both control and E2-stimulated tumours relative to normal ovary, whereas Esr2 was expressed at much lower levels in MASE-derived tumours." (PMID 29973689, 2018). "As the ESR1 mRNA level was already lower in the normal pituitaries of men compared to women, we suggested that early divergence of the ERα level and sex-associated regulation of estrogen signaling may have a major influence on vascularization, tumor growth, and chromosomic alteration." (PMID 30555413, 2018). "In vivo, STF-083010 significantly reduced tamoxifen resistant ESR1+ tumour growth both as a stand-alone therapy and in combination with tamoxifen." (PMID 30248920, 2018). "Because the target of activated CDK4/6 is Rb, pRb levels were examined by immunohistochemistry (IHC) in ESR1 fusion-expressing T47D xenograft tumor sections." (PMID 30089255, 2018). "These ESR1 and PIK3CA mutations coincide with increasing CA 27–29 levels in the blood, suggesting rapid genomic evolution and tumor progression." (PMID 30470782, 2018). "This is in line with previous studies that have reported a low level of ER/ESR1 expression in CTCs compared with the primary tumor in MBC." (PMID 28489591, 2017). "It is important to decipher if and how co-existing ESR1 mutant-cells interact, and if such interaction provides the tumor with an evolutionary advantage compared to single ESR1 mutant tumors." (PMID 28535794, 2017). "We present a patient with metastatic breast cancer whose tumor was found to have amplification of ESR1 by tumor genome sequencing." (PMID 28924522, 2017). "In the tumor samples analyzed in the present study, the ESR1 promoter was frequently (83%) found to be methylated (methylation status ≥ LOD)." (PMID 28403857, 2017). "In this study, we investigated the frequencies of the E380Q ESR1 mutation in comparison with the other ESR1 LBD mutations, Y537S, Y537N, Y537C, and D538G in tumor tissue and plasma DNA." (PMID 29166868, 2017). "This tumour had over 2.5-fold higher ESR1 mRNA expression levels at surgery than at baseline and was sensitive to aromatase-inhibitor treatment as determined by the drop in Ki67 level from 24 to 1%." (PMID 27502118, 2016). "The major findings reported herein are that ESR1 mutations are present in ∼40% of patients that have progressed on AI therapy and are numerically enriched in luminal A and PIK3CA-mutated tumours." (PMID 27174596, 2016). "Other demographic and clinical parameters were generally balanced between patients with ESR1 mutations and ESR1 WT patients, including age, race, region, Eastern Cooperative Oncology Group (ECOG) score, baseline tumour burden and others." (PMID 27174596, 2016). "As expected, GSEA revealed that oestrogen stimulation upregulates genes that are positively regulated by ESR1 in tumours." (PMID 27236187, 2016).
tumor (continued). "We therefore split the regulon into a group of activated and a group of repressed genes, based on the Pearson’s correlation of gene expression between ESR1 and each target in tumours." (PMID 27236187, 2016). "The HER2-amplified luminal tumours, showing significantly lower ESR1 expression levels than ordinary-luminal, presumably originate from an earlier development stage than luminal A (or luminal Q1/Q2)." (PMID 27341628, 2016). "ESR1 mutations are present in 37% of baseline samples and are enriched in patients with luminal A and PIK3CA-mutated tumours." (PMID 27174596, 2016). "When considering the estimation of the percentage of tumor cells harboring the mutation, i.e., CCF, we found that ESR1 and RB1 mutations were mostly identified as subclonal (ESR1: 14/21 mutations [67%]; RB1: 5/10 mutations [50%])." (PMID 28027327, 2016). "High FoxA1 gene expression significantly correlated with high expression of well-established luminal markers, such as GATA3 and ESR1, in primary tumours." (PMID 27045898, 2016). "Seminal work published by Kwabi-Addu and his coauthors in the Clinical Cancer Research showed that methylation of GSTPi, RARβ2, RASSF1A, NK2 homeobox 5 (NKX-2-5), and estrogen receptor 1 (ESR1) tumours suppressor genes in prostate tissues is age-independent." (PMID 27891254, 2016). "Estrogen receptor (ER) signalling via ESR1 and 2 also regulates the tumour-promoting and tumour-suppressive effects of the immune response in several human malignancies." (PMID 25970543, 2015). "Tumour ESR1 gene expression (Hazard Ratio [HR] for relapse 2.33, 95% CI 1.35-4.02; HR for death 1.74, 95% CI 1.02-2.97) and absence of necrosis (HR for relapse 1.71, 95% CI 1.05-2.71; HR for death 1.98, 95% CI 1.14-3.43) were adverse prognostic features." (PMID 25970543, 2015). "There was an additional deletion in the distal end of 6q (6q25.1-6q27) apparent only in the TN tumor, covering the entire ESR1 locus." (PMID 26554380, 2015). "We then applied absCN-seq to estimate the absolute copy numbers for the ESR1 region and found that the HR+ tumor has two copies and the TN tumor only one copy for this region." (PMID 26554380, 2015). "The PAM50 qRT-PCR assay was used to: a) assess tumor gene expression levels for ESR1, PGR, ERBB2, and 10 proliferation genes and b) classify tumors into intrinsic subtype (Luminal A, Luminal B, Basal-like, HER2-enriched, Normal-like)." (PMID 25884832, 2015). "ESR1 IHC staining was used to determine if any enriched MEC subgroups developed tumors with extensive ESR1-positive (ER+) cells, as defined by strong nuclear staining in 20 % or more of tumor cells." (PMID 26429062, 2015). "For the key gene in our analyses, ESR1, the tumor normal correlation is 0.096 while the correlation between double primaries is 0.517, indicating only modest inflation." (PMID 25974664, 2015). "The observed intragenic ESR1 methylation in epithelial cells extracted from human breast milk confirmed the in vitro cell line findings of high levels of IGM in ER-positive tumour cell lines, and low levels of promoter methylation." (PMID 25927974, 2015). "The respective mutation in each case was detected by whole-exome sequencing of the tumor relative to the matched normal sample and was corroborated by whole-transcriptome sequencing, as ESR1 was expressed at moderate to high levels." (PMID 26561834, 2015). "Tumour ESR1 mRNA expression was an adverse prognostic factor, independently correlating with relapse (HR = 2.86, 95% CI 1.60–5.12, p = 0.0004) and death (HR = 1.95, 95% CI 1.10–3.46, p = 0.022)." (PMID 25970543, 2015). "These two observations make ESR1 a strong candidate regulator for the process of establishing a tumor-prone environment." (PMID 24464994, 2014).
tumor (continued). "We identified ESR1 as a key regulator of establishing a tumor-prone environment and we identified NFE2 as a key regulator of the sustained xenobiotic response." (PMID 24464994, 2014). "We propose novel roles for E2F and ZFP161 in PB-mediated hepatocyte proliferation and suggest that PB-mediated suppression of ESR1 activity contributes to the development of a tumor-prone environment." (PMID 24464994, 2014). "Our work reveals a novel regulatory mechanism of ESR1 basal turnover and activity and an unanticipated relationship with the pRb tumor suppressor." (PMID 23900261, 2013). "ESR1 inhibits cell migration and the repression of ESR1 expression enhances cell migration and accelerates tumour formation and metastasis." (PMID 24555436, 2013). "Genes whose expression is tightly regulated by ESR1 can also be correlated with the ER-status of a tumor." (PMID 24312637, 2013). "High tumor ESR1 mRNA expression significantly correlated with improved patient survival (HR for OS 0.74, p = 0.04), though not with superior DFS." (PMID 23923010, 2013). "We suggest that the combination of the ESR1-specific intra-tumor heterogeneity and low-level copy number increase accounts for these discrepancies." (PMID 24367641, 2013). "In contrast, EGFR/HER1 expression levels correlated negatively with ESR1 tumour levels (r=-0.629, P=0.012) in addition to intratumour (r=-0.633, P=0.001), normal tissue (r=-0.556, P=0.005) and plasma (r=-0.625, P=0.002) E2 levels." (PMID 23991224, 2013). "The 40-ΔCt mRNA value distribution of ESR1 had a median value of 40.5 (range 28.5–46) and 654 tumours had ESR1 mRNA values higher than the 25th distribution percentile." (PMID 23923010, 2013). "ESR1-positive tumours have broadly better outcomes, with slower-growing tumours on the whole, fewer metastases, and a greater range of hormonally targeted treatment options including tamoxifen and the aromatase inhibitors." (PMID 22166804, 2012). "Previous studies have reported that tumor specimens from women of African-American heritage are significantly more likely to lack expression of the hormone receptors ESR1, PGR, and AR, compared to other ethnicities." (PMID 22616718, 2012). "One tumour was shown to be amplified and eight showed gains at ESR1, C6ORF96, C6ORF97 and C6ORF211, while four showed losses at all four loci." (PMID 21552322, 2011). "Intratumoral levels of estrogens have also been measured and were found correlated with tumor gene expression of estradiol-metabolizing enzymes and the estrogen receptor gene (ESR1) and of proliferation markers." (PMID 21812955, 2011). "We evaluated CXCL12 and ESR1 methylation in primary tumour samples by methylation-specific PCR (MSP)." (PMID 20109227, 2010). "The MSP technique was tested with CXCL12 (island 2 and island 4) and ESR1 genes in DNA from the tumour cell lines in order to confirm the results from RT-PCR and data from the literature (ESR1)." (PMID 20109227, 2010). "The dataset consists of expression profiles for genes related to the estrogen receptor gene ESR1 (also known as ER-alpha) derived from tumor samples." (PMID 21079769, 2010). "Since the tumour sub-classification based on gene expression is driven to a significant extent by expression of the estrogen receptor (ESR1), we studied its promoter methylation in normal samples as well as in a subset of the tumours." (PMID 20338046, 2010). "In a multivariate analysis including traditional prognostic factors (age, menopausal status, tumour size, grade and ESR1 and PGR mRNA levels), NCOR2 mRNA levels were significantly associated with a favourable MFS (median, HR=0.68, P=0.006) and OS." (PMID 19904269, 2009). "Tumours were initially segregated according to the expression of ESR1 gene or the expression of basal markers." (PMID 19826428, 2009).